ACRBP (acrosin binding protein)
Description:
[Acrosin-binding protein, mature form]: Acrosomal protein that maintains proacrosin (pro-ACR) as an enzymatically inactive zymogen in the acrosome. Involved also in the acrosome formation.
Synonyms: CT23; SP32; OY-TES-1
Tractability: Antibody: UniProt places it where antibodies can reach, with medium confidence; UniProt predicts a signal peptide or a membrane-spanning region; its Gene Ontology location is reachable by antibodies, with medium confidence.
Gene: Protein-coding gene on chromosome 12 (6,638,075 to 6,647,433, reverse strand). Ensembl gene ENSG00000111644.
Subcellular location: Secreted; Cytoplasmic vesicle, secretory vesicle, acrosome
Subcellular location (Human Protein Atlas): Nucleoplasm; Vesicles; Cytosol; Predicted to be secreted
Gene Ontology:
Biological process: acrosome assembly; fertilization; spermatid development
Cellular component: nucleus; acrosomal membrane; acrosomal vesicle; extracellular region
Genetic constraint (gnomAD): Loss-of-function variants: 51 observed, 70.67 expected, observed/expected ratio (o/e) 0.72, 90% interval 0.57 to 0.91. The upper end of that interval is the gene's LOEUF score, 0.91, which puts it in group 3 of 6, group 1 being the genes least tolerant of losing a copy. Missense variants: 603 observed, 696.35 expected, observed/expected ratio (o/e) 0.87, 90% interval 0.81 to 0.93. Synonymous variants: 266 observed, 270.21 expected, observed/expected ratio (o/e) 0.98, 90% interval 0.89 to 1.09.
Homologues: Orthologues: chimpanzee ACRBP (99% identical), macaque ACRBP (95% identical), rabbit ACRBP (85% identical), pig ACRBP (83% identical), guinea pig ACRBP (77% identical), mouse Acrbp (75% identical), rat Acrbp (75% identical), dog ACRBP (74% identical).
Diseases named in the same sentence as ACRBP in open-access papers:
ACRBP is named in the same sentence as 22 diseases in open-access papers, as found by Europe PMC text mining. Sharing a sentence is not in itself a finding about the gene and the disease. The quoted sentences say what the papers report.
ovarian carcinoma (5 papers, 2016 to 2024). A malignant neoplasm originating from the surface ovarian epithelium. "ACRBP exhibits a broad expression pattern in several cancers, including ovarian, lung (NSCLC), breast, bladder, colon and liver, and high expression of ACRBP is associated with a poor clinical outcome in ovarian cancer patients with reduced survival time and faster relapse." (PMID 27275820, 2016). "As such, depletion of ACRBP in ovarian cancer cells treated with paclitaxel resulted in elevated NuMa levels, activating the spindle assembly checkpoint response, and leading to mitotic delay, mitotic catastrophe and subsequently enhanced treatment response." (PMID 38596293, 2024). "High ACRBP expression in ovarian cancer correlates with reduced survival, earlier relapse and paclitaxel resistance." (PMID 38596293, 2024). "ACRBP mRNA and protein expressions were upregulated in OC tissues relative to normal tissue, especially highly expressed in epithelial ovarian cancer (EOC)." (PMID 34528758, 2021). "Together with its restricted expression pattern and high specificity to cancer cells, ACRBP could be a potential target for prognostic evaluation and tumor‐specific antigen‐based immunotherapy for patients with ovarian cancer." (PMID 34528758, 2021). "This study aimed to evaluate ACRBP expression and immunogenicity in ovarian cancer (OC)." (PMID 34528758, 2021). "Using a synthetic lethal RNA interference screen, the CTA ACRBP (acrosin binding protein) was identified in non-small cell lung (NSCLC) and ovarian cancers to be essential for bipolar spindle formation as a consequence of its regulation of NUMA accumulation." (PMID 36980267, 2023). "Acrosin Binding Protein (ACRBP) was shown to support mitotic fidelity and promote resistance towards paclitaxel in ovarian cancer." (PMID 27275820, 2016).
breast carcinoma (4 papers, 2015 to 2021). "In humans, the ACRBP expression is usually limited in testes in general, however, it could be detected in various tumor types like bladder, lung, and breast cancer." (PMID 32628820, 2020).
glioma (2 papers, 2021). A benign or malignant brain and spinal cord tumor that arises from glial cells (astrocytes, oligodendrocytes, ependymal cells). "ACRBP mRNA transcripts were expressed in glioma and anti-ACRBP antibodies were found in patient sera." (PMID 34681642, 2021). "Li and coworkers found antibodies toward sperm-specific protein ACRBP in the serum of their glioma patients." (PMID 34681642, 2021). "Li and co-workers examined both levels of ACRBP in glioma and the peripheral B-cell response to this protein in glioma patients." (PMID 34681642, 2021). "Elevated ACRBP mRNA expression can be detected in various tumor tissues and cell lines, such as glioma, hepatocellular carcinoma, and colon cancer." (PMID 34528758, 2021). "In addition, ACRBP existed in many other tumors such as hepatocellular carcinoma, colorectal cancer, and glioma according to previous studies." (PMID 34528758, 2021).
infertile (2 papers, 2021). "Proteomic analysis verified that acrosome-related proteins, including acrosin-binding protein (ACRBP), were downregulated in infertile sperm." (PMID 34070710, 2021). "A recent study highlighted the importance of ACRBP in human fertility, showing that an under-representation of ACRBP peptides in infertile men impaired capacitation." (PMID 34086710, 2021). "Proteomic and immunofluorescence analyses verified that acrosome-related proteins, including acrosin-binding protein (ACRBP) and sperm equatorial segment protein 1 (SPESP1), were downregulated in infertile sperm." (PMID 34070710, 2021).
male infertility (2 papers, 2018 to 2021). The inability of the male to effect fertilization of an ovum after a specified period of unprotected intercourse. "Transgenic mice, lacking protein convertase subtilisin/kexin type 4 displayed difficulties in converting the precursor form of ACRBP to mature ACRBP, which was accompanied by extensive male infertility." (PMID 34086710, 2021). "The biggest interaction network contained 31 nodes including several down-regulated proteins associated with sperm-oocyte interaction, e.g. acrosin-binding protein (ACRBP) and zona pellucida-binding protein 1 (ZPBP1), which displayed the complexity of the mechanisms under the male infertility." (PMID 30166971, 2018).
Fibroadenoma (1 paper, 2015). A benign tumor of the breast characterized by the presence of stromal and epithelial elements. "ACRBP, ODF4 and RHOXF2 were expressedin 60, 10 and 10% of fibroadenomas respectively.None of the fibroadenoma samples showed SPATA19expression." (PMID 26464818, 2015).
follicular lymphoma (1 paper, 2025). Follicular lymphoma is a form of non-Hodgkin lymphoma characterized by a proliferation of B cells whose nodular structure of follicular architecture is preserved. "Furthermore, a four-gene panel comprising CNN2, HMG20B, ACRBP, and IZUMO1 successfully distinguished DLBCL from follicular lymphoma (FL), achieving an AUC of 0.89 in the testing set, regardless of the cell-of-origin or stage of DLBCL." (PMID 40055844, 2025).
Globozoospermia (1 paper, 2016). Any structural anomaly of the acrosome resulting in a round sperm head. "The acrosomal matrix protein ACRBP was recently identified as another globozoospermia-related protein to regulate acrosomal granule formation." (PMID 27831554, 2016).
hepatocellular carcinoma (1 paper, 2021). A malignant tumor that arises from hepatocytes. "In a previous study, we found that knockdown of ACRBP inhibits cell proliferation, prevents migration and invasion, arrests cell cycle, and promotes cell apoptosis of human mesenchymal stem cells (MSCs) and hepatocellular carcinoma cells." (PMID 34528758, 2021).
mesothelioma (1 paper, 2025). A usually malignant and aggressive neoplasm of the mesothelium which is often associated with exposure to asbestos. "The proteins that were unique to mesothelioma samples (cell line and PE samples) were MAGED4, PRAME, WT1, ACRBP, EPHA2 and SOX11." (PMID 39921204, 2025).
cancer (9 papers, 2012 to 2024). A tumor composed of atypical neoplastic, often pleomorphic cells that invade other tissues. "Serological surveys detected antibodies against ACRBP in 3.5%–22.2% of patients with different types of cancer." (PMID 34528758, 2021). "ACRBP is a testisselective genewhich has been shown to be expressed in a varietyof cancers at the transcript level and inovarian cancer at the protein level." (PMID 26464818, 2015). "Brother of the regulator of imprinted sites (BORIS), acrosin binding protein (ACRBP), synaptonemal complex protein 1 (SYCP1), and transmembrane protein 31 (TMEM31) cancer/testis antigens have utilized for in silico peptide vaccine design due to their high expression in various tumors." (PMID 38923980, 2024). "NY-SAR-35 antigen, previously unexplored in bioinformatics, shares characteristics with BORIS, TMEM31, ACRBP, and SYCP1 in terms of its high expression on the cancer cells, notable immunogenicity, and absence of expression on the normal cells." (PMID 38923980, 2024).
tumor (7 papers, 2012 to 2024). "ACRBP is normally expressed exclusively in the human testis but is also expressed in a wide range of different tumor types." (PMID 35327169, 2022). "Of 16 antibody‐positive sera, there were 7 (7/46, 15.2%) patients with an ACRBP high expression tumor, and 9 (9/19, 47.3%) patients with an ACRBP low expression tumor." (PMID 34528758, 2021). "And those sera antibody‐positive patients with ACRBP high expression tumor include one in Stage II and six in Stages III and IV, whereas sera antibody‐positive patients with ACRBP low expression tumor include four in Stage I–II and five in Stages III–IV." (PMID 34528758, 2021). "By contrast, tumor cells showed prominent ACRBP expression, especially in the glandular region." (PMID 34528758, 2021). "ACRBP expression was upregulated in OC tissues and induced humoral immune response in patients with OC, suggesting that ACRBP is a potential prognostic biomarker and a target of tumor immunotherapy for OC." (PMID 34528758, 2021). "Hence, ACRBP, similar to the other members of CT antigens, could be a potential target for tumor‐specific antigen‐based immunotherapy for patients with OC." (PMID 34528758, 2021). "In addition, ACRBP was also detected in 7.1% (4/56) of the serum samples of patients with Stages III and IV OC burdened with ACRBP high expression tumor." (PMID 34528758, 2021). "The effects of ACRBP on OC progression were investigated by analyzing the correlation between ACRBP expression and the clinicopathological parameters of patients with OC, including age, FIGO stage, tumor grade, histopathology, serum CA125 level, lymph node metastasis, and chemosensitivity." (PMID 34528758, 2021).
adenocarcinoma (1 paper, 2015). A common cancer characterized by the presence of malignant glandular cells. "Previous studies by others have indicated that silencing of ACRBP (testis cancer antigen) or TUBGCP2 (microtubule-associated protein) did not affect cell viability but did enhance taxol-induced mitotic arrest in H1299 and H2126 cells (NSCLC, adenocarcinomas)." (PMID 26086592, 2015).
ACRBP also shares sentences with these, for which no sentence is quoted: liver cancer (2 papers); lung carcinoma (2); bladder cancer (1); colon cancer (1); colorectal cancer (1); ductal carcinoma (1); leukemia (1); melanoma (1); triple-negative breast carcinoma (1).